HIF1A (hypoxia inducible factor 1 subunit alpha)
Diseases named in the same sentence as HIF1A in open-access papers (continued):
Sharing a sentence is not in itself a finding about the gene and the disease.
tumor (continued). "The mechanism underlying the anti-tumor effect of pristimerin involves in cell cycle arrest, apoptosis, necrosis and autophagy that regulated by ROS/ASK1/JNK, HIF-1α, NF-κB signaling pathway." (PMID 32286274, 2020). "In glycolytic tumor cells, HIF-1α and MYC upregulate MCT-4 to promote the secretion of lactate into the TME." (PMID 32528879, 2020). "Melatonin influenced hypoxia-inducible factor-1α (HIF-1α), a major oncogenic factor playing an essential role in tumor invasion and angiogenesis under hypoxia, as well as the activity of the enzymes responsible for the degradation of HIF-1α." (PMID 32138190, 2020). "To understand the role of HIF-1α on tumor growth, we sorted MC-38GFP tumor cells from orthotopic HIF-1α-KD and Mock tumors and analyzed the transcriptome using RNA sequencing." (PMID 33142239, 2020). "In tumour cells, HIF1α-induced uptake and reduction of glutamine induces lipid synthesis and storage in lipid droplets (LD)." (PMID 33257753, 2020). "HIF1A induces tumor hypoxia driving uPAR expression through a hypoxia responsible element (HRE) in the uPAR promoter." (PMID 32010430, 2020). "TRIM44, USP20 and USP7 also stabilizes HIF-1α by deubiquitination, leading to tumor progression under hypoxia." (PMID 33004065, 2020). "We found that IDF-11774 effectively suppressed HIF-1α by accelerating its degradation, and successful suppression of HIF-1α resulted in the attenuation of tumor progression in terms of proliferation, migration, and invasion." (PMID 32847004, 2020). "Anticancer drug glyceollins and thymoquinone can inhibit tumor growth by elevating ubiquitination and degradation of HIF-1α." (PMID 33004065, 2020). "Meanwhile, immunohistochemistry (IHC) staining for endogenous markers of hypoxia with HIF‐1α antibody also confirmed that the tumor was indeed more hypoxic than the normal liver, with about 10‐fold higher HIF‐1α staining." (PMID 32537394, 2020). "Accumulated evidence has demonstrated that HIF-1α has a dominant role in tumor progression, and HIF-1α-regulation of expression of VEGFA is regarded as the main inducer of angiogenesis." (PMID 32273947, 2020). "As already described, LMWHs inhibit VEGF via TFPI release and alleviate hypoxia in the TME, thus downregulating the expression of HIF-1a and further driving the tumor toward normoxia." (PMID 32069809, 2020). "We further demonstrate a reciprocal regulation between PRKAR2B and HIF‐1α and this loop have a critical role in the Warburg effect and tumour growth." (PMID 33025691, 2020). "HIF-1α is a transcriptional factor for many genes that code for various proteins involving tumor cell proliferation and survival, angiogenesis, glucose metabolism, and invasion and metastasis pathways." (PMID 33374849, 2020). "In this regard, we have provided evidence indicating that tumor-derived MDSCs are more immunosuppressive than splenic MDSCs mostly because of the induction of HIF-1α-dependent increased arginase activity and nitric oxide production." (PMID 33552076, 2020). "The only mutation that occurred more frequently in the HIF1A loss subgroup than the unaltered subgroup was BAP1, which was detected in 9% of all ccRCC tumours." (PMID 32807776, 2020). "Similar to GBE1, HIF1α is increased in late-stage tumors and is closely correlated with tumor progression." (PMID 32439898, 2020). "FBX8 not only maintains the stemness of tumor cells but also regulates the biological functions of dormant tumor cells by targeting HIF-1α, CDK4, and C-Myc." (PMID 32796813, 2020). "Another study further confirmed that in breast cancer, Parkin inhibited tumor migration and invasion through targeting HIF-1α for ubiquitination and degradation." (PMID 32587855, 2020).
tumor (continued). "Here, we report that tumor samples showed significant upregulation of HIF-1α expression compared to the control tissues." (PMID 32707933, 2020). "HIF-1α is a prominent transcription factor for the transcription of the genes which are responsible for tumor development and invasion under hypoxic conditions." (PMID 33195038, 2020). "In HCC, CDK5 is highly expressed in tumor tissues, regulates DNA damage response, and promotes angiogenesis through interactions with inducible hypoxia factor 1α (HIF-1α)." (PMID 32018226, 2020). "Hypoxia-inducible factor (HIF)-1α was found to alter the function of MDSC dramatically in the tumor microenvironment and redirected their differentiation towards tumor-associated macrophages." (PMID 32443699, 2020). "Neoplastic cells with HIF-1α overexpression were scattered throughout the neoplasm and frequently observed nearby the necrosis." (PMID 32375802, 2020). "In reflecting tumor hypoxia, HIF-1α was positively correlated with R2∗ value (r = 0.721, P < 0.001) but inversely correlated with D∗ (r = −0.582, P = 0.003) and f values (r = −0.609, P = 0.002)." (PMID 33134165, 2020). "Immunohistochemical analyses were used to detect the expression level of GLUT3 and HIF-1α in the tumor specimens." (PMID 32908869, 2020). "The PI3K/AKT/mTOR signaling pathway is an essential component of the glycolysis in tumor cells; it upregulates HIF-1α and then increases the LDHA expression, thus shifting metabolism to aerobic glycolysis." (PMID 32076440, 2020). "Quantitatively speaking, in early stages of tumor growth, the average relative expression level of Hif1α, VEGFR1 and VEGFR2 were 3.48- (P < 0.05), 0.75- (P < 0.05) and 7.6-fold (P < 0.01), respectively, in comparison to healthy controls." (PMID 32373503, 2020). "Taken together, our results indicate that Sdc-3 expression is hypoxia-sensitive and depends on HIF-1α activity in tumor cells." (PMID 33117401, 2020). "These in vivo results indicate an essential role for CEP41 in tumor angiogenesis that is likely attributable to its activation of HIF1α in ECs under hypoxic conditions." (PMID 31885126, 2020). "In advanced stages of tumor growth, the expression level of Hif1α, VEGFR1 and VEGFR2 were 15.28- (P < 0.001), 13.40- (P < 0.01) and 16.13 fold (P < 0.01)." (PMID 32373503, 2020). "Glycolysis in tumor cells is tightly regulated by a couple of known transcription factors: c-Myc, N-Myc, HIF1α and others through binding to the promoter regions of key glycolytic enzymes and transporters and are facilitators of the Warburg effect." (PMID 32258244, 2020). "In HIF-1α-KD tumor cells we found 280 genes significantly upregulated (P< 0.05), while 288 genes were downregulated when compared to Mock tumor cells." (PMID 33142239, 2020). "Herein, we demonstrate that GBE1 is an important transcriptional target of HIF1α signaling and can promote tumor progression by regulating the methylation of FBP1 via the NF-κB signaling pathway in LUAD cells." (PMID 32439898, 2020). "The overexpression and stabilization of the protein HIF-1α do not only result from low oxygen levels within the microenvironment, but also promote the advancement of hypoxia and facilitates tumor cell survival within the hypoxic microenvironment." (PMID 33680952, 2020). "αSMA is a well-established marker for stromal activation, and the correlation indicates a strong correlation between hypoxia (as evident from HIF1α activation in both the tumor and the stroma cells), and stroma activation." (PMID 33105540, 2020). "Dormancy induction mediated by HIF-1α segregated by stem-like tumor cells in the peri-necrotic niche favors tumoral recurrence, decreasing the survival of GBM patients that received the standard therapy (surgery followed by radiation and chemotherapy [TMZ])." (PMID 32707662, 2020). "The least distinct differences in POX, PPARγ and HIF1-α expression occurred in the group of highly differentiated tumours (G1)." (PMID 31935820, 2020).
tumor (continued). "They inferred that LMP1serves ERK1/2 signaling pathway for targeting NF-κB as its downstream event to excite HIF-1α gene promoter activity and facilitates tumor progression." (PMID 33072180, 2020). "In another study a miR-183-96-182 cluster overexpressed the master regulator of angiogenesis HIF-1a augmenting tumour progression and angiogenesis." (PMID 32116694, 2020). "Conversely, inactivation of AMPK has been shown to increase HIF-1α expression, which in turn increases aerobic glycolysis and cellular biosynthesis in tumor cells." (PMID 32596143, 2020). "Previous studies had reported that several other miRNAs, such as miR-18a and miR-497, exerted an anti-tumor activity in BC through targeting HIF1A." (PMID 32831653, 2020). "Analysis of tumor infiltrating cells revealed a reduced number of granulocytes (Ly6G+ cells), but increased presence of inflammatory monocytes (Ly6C+ cells) in HIF-1α-KD tumors, when compared to Mock tumors." (PMID 33142239, 2020). "In physiological conditions, the levels of HIF-1α are regulated by the von Hippel–Lindau (pVHL) tumor suppressor, which continuously targets HIF-1α for proteasomal degradation." (PMID 32985545, 2020). "The roles of the CLDN6/SENP1/HIF-1α signaling on tumor metastasis were evaluated by function experiments and clinical samples." (PMID 32093760, 2020). "Intracecal injection of HIF-1α-KD cell resulted in reduced tumor growth when compared to control MC-38 (Mock) cells." (PMID 33142239, 2020). "Disregulated PI3K activation in tumours can enhance CAIX expression via a mechanism dependent on HIF-1α translation by mTOR." (PMID 36046070, 2020). "This study identifies a novel hypoxia-inducible target gene, ALS2, which is overexpressed in a HIF-1α-related malignancy and promotes the acquisition of aggressive traits in tumor cells." (PMID 33339852, 2020). "Apart from its transcriptional regulation function, YB1 translationally activates a set of mRNAs whose protein products are involved in the process of embryonic development and tumor progression, such as Snail, twist, HIF1a and MYC." (PMID 32028981, 2020). "Upregulation of HIF1A protein in tumor tissues can be achieved by promoting DNA transcription, enhancing mRNA translation, or inhibiting proteasomal degradation." (PMID 32894161, 2020). "This limits the therapeutic specificity of targeting HIF1α and risks unintended side effects as a result of a drug’s effects on HIF1α expression in non-tumor tissues." (PMID 32938997, 2020). "VEGF is not only a positive control for HIF-1α, but also a well-known marker for angiogenesis and tumor growth." (PMID 32858793, 2020). "A sustained presence of undegraded HIF-1α in the hypoxic tumor core can also correlate to differentiation checkpoints for Treg or Th17 cells, and an upregulation of PD-1 ligand expression on cancer cells." (PMID 32357910, 2020). "Many recent studies have provided convincing evidence of strong correlations between elevated levels of HIF-1α and tumor metastasis, angiogenesis, and tumor resistance to therapy." (PMID 32045997, 2020). "HIF1A has been recognized as a strong promoter of tumor growth and it is responsible for VEGF gene expression." (PMID 33109189, 2020). "The induction of glucose transporters is tightly linked with the induction of hypoxia‐inducible factor 1‐alpha (HIF‐1α), a factor able, in turn, to increase tumor metabolism, stimulate vascular angiogenesis and mitosis associated factors." (PMID 32945604, 2020). "ccRCC tumours that express only HIF-2α have higher proliferation rates than those expressing HIF-1α and HIF-2α21." (PMID 32807776, 2020). "HIF-1α functions as a master regulator of hypoxia-mediated tumour metastasis mainly by promoting EMT through directly upregulating TWIST and SNAI expression." (PMID 32093760, 2020). "In summary, these results identify a SNHG11/ HIF-1α axis that plays a pivotal role in tumor invasion and metastasis." (PMID 33060856, 2020).
tumor (continued). "The expression of transcription factors regulating angiogenesis, such as HIF‐1α, is constitutively observed in macrophages that are located in hypoxic tumour sites." (PMID 32735377, 2020). "This HIF-1α-related immunosuppression can inhibit anti-tumor effects and give strong evidence for supplemental oxygen application in cancer therapies." (PMID 32033172, 2020). "HIF inhibitors in clinical studies have shown modest results and high toxicity, therefore, HIF inhibition should be approached in a more holistic way, modulating for example the external factors that lead to HIF-1α activation in the tumor context." (PMID 32850424, 2020). "And concurrent with the notion that hypoxic tumours are radioresistant, depletion of HIF-1α in tumour models radiosensitises cells." (PMID 32864165, 2020). "Pancreatic carcinomas compared to benign tumors show higher levels of the expression of the HIF-1α protein, more tumor proliferation, and less tumor differentiation." (PMID 33195038, 2020). "IHC assay showed that the DKC1 knockdown xenograft tumour HIF-1α and VEGF protein expression was decreased compared with the control group." (PMID 31857720, 2020). "For example, cellular signaling via HIF1α, extracellular acidity generated by the lactate released by both tumor and stromal cells, and metabolic competition for nutrients within the TME can all significantly alter the progress of tumorigenesis." (PMID 33067808, 2020). "Activation and stabilization of the HIF-1α signaling pathway induce the expression of many target genes involved in tumor cell growth, metabolism, and invasion." (PMID 33344242, 2020). "VHL, a tumor suppressor, functions as part of a ubiquitin ligase complex that recognizes HIF-1α as a substrate and is part of the oxygen-sensing mechanism of the cell." (PMID 33013381, 2020). "Melatonin degrades and inhibits HIF1-α in tumours, thereby increasing apoptosis, again indicating the impact that variations in local melatonin production can have on core tumour regulators." (PMID 33375613, 2020). "Hypoxic microenvironment will change the metabolism of tumor cells, induce adaptive changes in cell metabolism, and regulate complex cellular signaling pathways such as HIF-1α and NF-κB." (PMID 32031203, 2020). "Studies in skin, breast, gastric, brain, salivary gland, and pulmonary cancer have shown the role of these proteins in promoting tumour progression, where the hypoxia-inducible factor 1 alpha (HIF-1α) plays a regulatory role." (PMID 33067558, 2020). "Through these activities, HIF-1α expression in Treg cells confers anticancer immunity, which protects hosts from tumor growth." (PMID 33024109, 2020). "Increased PN expression would also contribute to tumor cell survival during hypoxia through the overexpression of hypoxia-inducible factor (HIF)-1α." (PMID 33255560, 2020). "For example, lactate produced by tumor cells induces pro-tumorigenic TAMs through a mechanism mediated by HIF1α." (PMID 33374253, 2020). "HIF-1α upregulation has also been shown to significantly govern the suppressive activity of MDSCs in the tumor microenvironment." (PMID 32121028, 2020). "In tumor-mediated hypoxia, activated HIF-1α can simultaneously induce PD-L1 and PKM2 expression, influencing immune evasion and glycolysis." (PMID 32489463, 2020). "HIF-1α also induces angiogenesis, to ensure the availability of oxygen and nutrients for the survival of tumor cells, through the transcriptional regulation of VEGF." (PMID 32707662, 2020). "Many compounds, including natural compounds, influence the tumor microenvironment by regulating HIF-1α expression and can dysregulate glucose metabolism." (PMID 32806533, 2020). "As a key regulator of tumor hypoxia response, HIF-1α is a key transcriptional regulatory protein that regulates many key genes." (PMID 33027968, 2020).
tumor (continued). "Overall, fluorescence micrographs show more abundant HIF-1α in the tumour core than in the middle region, consistent with the greater hypoxia in the core." (PMID 32337021, 2020). "Mice bearing RT-R-MDA-MB-231 xenografts expressed a significantly higher level of HIF-1α in tumor tissue and significantly increased plasma LOX levels compared to those with MDA-MB-231 cells." (PMID 33126606, 2020). "The genes that appeared to be regulated by HIF-1α in ASC-overexpressing cells were significantly elevated in RNA-seq data obtained from tumor tissues annotated in the OSCC-Taiwan and OSCC-TCGA databases." (PMID 32883954, 2020). "SDH mutations result in the accumulation of succinate and subsequent stabilization of HIF-1α, an essential regulator of glycolysis and stress response, and relevant to tumor growth." (PMID 33409279, 2020). "Very recently, HIF-1α expression was reported to correlate with increased tumor immune and stromal signatures and aggressive phenotypes in human cancer." (PMID 33552076, 2020). "Hif1a has been intensively studied as a critical regulator of T cell function, disease pathophysiology, and tumor microenvironment, and is thus considered a potential target for drug development." (PMID 33644036, 2020). "Our data indicate that TRAF6-HIF-1α interaction contributes to tumor growth, primarily through modulation of angiogenesis, likely through stabilization of HIF-1α proteins levels in tumor cells." (PMID 33142239, 2020). "With tumor tissues growing, one of the critical mediators of hypoxic responses is the hypoxia-inducible factor 1α (HIF-1α)." (PMID 32322211, 2020). "HIF-1α, a Ca2+-sensitive factor, has been confirmed to be involved in tumor cell metastasis by promoting EMT." (PMID 32152662, 2020). "In the presence of oxygen, the tumour suppressor von Hippel–Lindau (pVHL) protein targets HIF-1α for proteasomal degradation by means of proline hydroxylation using O2 and α-ketoglutarate as substrates." (PMID 32570870, 2020). "HIF-1α is a transcription factor regulating tumor cell survival and proliferation; and epithelial barrier function following inflammation in the colon." (PMID 33142239, 2020). "For example, the hypoxic TME leads to HIF-1α signalling, which aids in MDSC differentiation to tumour-promoting tumour-associated macrophages (TAMs)." (PMID 33092283, 2020). "Effect of Nb@IC-NPs on enhancing A549 tumor hypoxia and expression profile of HIF-1α was investigated in the presence of NIR." (PMID 33292202, 2020). "Hypoxia inducible factor-1α (HIF-1α) induced in the tumor microenvironment leads to the release of lysyl oxidase (LOX), which mediates collagen crosslinking at distant sites to facilitate environmental changes that allow cancer cells to easily metastasize." (PMID 33126606, 2020). "Our data strongly supports the role of CLDN6 in mediating hypoxia-induced tumour metastasis, at least partially by mediating HIF-1α." (PMID 32093760, 2020). "Although the hypoxia response in tumor cells is well understood, the role of constitutively activated hypoxia-inducible factor (HIF)-1α in normoxic conditions is less known." (PMID 33396270, 2020). "Overall, while the role of HIF-1α in rewiring glucose and AA metabolism is clearly directed to support tumor growth, the impact of hypoxia on lipid metabolism and its biological meaning is not univocal." (PMID 33291643, 2020). "A combination of radiotherapy and HIF-1α inhibitors showed similar results, increasing the tumor’s sensitivity to radiation." (PMID 33135539, 2020). "Hypoxia-induced angiogenesis of the tumor, due to an increased release of HIF-1α, leads to a significant overexpression of VEGF, which usually increases the average microvascular density in the tissue." (PMID 32488850, 2020).